DAZAP2 (DAZ associated protein 2)
Description:
In unstressed cells, promotes SIAH1-mediated polyubiquitination and degradation of the serine/threonine-protein kinase HIPK2, probably by acting as a loading factor that potentiates complex formation between HIPK2 and ubiquitin ligase SIAH1. Enhances the binding of transcription factor TCF7L2/TCF4, a Wnt signaling pathway effector, to the promoters of target genes (By similarity). Plays a role in stress granule formation.
Synonyms: KIAA0058; PRTB
Tractability: PROTAC: UniProt records ubiquitination sites on it; ubiquitination databases record sites on it.
Gene: Protein-coding gene on chromosome 12 (51,238,724 to 51,271,362, forward strand). Ensembl gene ENSG00000183283.
Subcellular location: Cytoplasm; Nucleus; Nucleus speckle; Nucleus, nuclear body; Cytoplasm, Stress granule
Subcellular location (Human Protein Atlas): Nuclear speckles
Gene Ontology:
Molecular function: DNA-binding transcription factor binding; identical protein binding; protein binding; protein serine/threonine kinase binding; ubiquitin protein ligase binding; WW domain binding; transcription coactivator activity; mitogen-activated protein kinase kinase kinase binding; protein serine/threonine kinase activator activity; receptor tyrosine kinase binding
Biological process: protein destabilization; stress granule assembly; positive regulation of DNA-templated transcription
Cellular component: cytoplasm; cytoplasmic stress granule; nuclear body; nuclear speck; nucleus; protein-containing complex
Genetic constraint (gnomAD): Loss-of-function variants: 3 observed, 16.95 expected, observed/expected ratio (o/e) 0.18, 90% interval 0.08 to 0.46. The upper end of that interval is the gene's LOEUF score, 0.46, which puts it in group 2 of 6, group 1 being the genes least tolerant of losing a copy. Missense variants: 169 observed, 221.21 expected, observed/expected ratio (o/e) 0.76, 90% interval 0.67 to 0.87. Synonymous variants: 69 observed, 80.09 expected, observed/expected ratio (o/e) 0.86, 90% interval 0.71 to 1.05.
Homologues: Orthologues: chimpanzee DAZAP2 (100% identical), guinea pig DAZAP2 (100% identical), dog DAZAP2 (99% identical), macaque DAZAP2 (99% identical), mouse Dazap2 (99% identical), pig DAZAP2 (99% identical), rat Dazap2 (98% identical), rabbit DAZAP2 (97% identical), tropical clawed frog dazap2 (74% identical), zebrafish dazap2 (61% identical), Drosophila melanogaster CG34125 (29% identical).
Diseases named in the same sentence as DAZAP2 in open-access papers:
DAZAP2 is named in the same sentence as 12 diseases in open-access papers, as found by Europe PMC text mining. Sharing a sentence is not in itself a finding about the gene and the disease. The quoted sentences say what the papers report.
multiple myeloma (5 papers, 2012 to 2025). "The results implicated a role for DAZAP2 as a potential tumor suppressor involved in the origin and development of multiple myeloma." (PMID 22792345, 2012). "In this report, we analyzed epigenetic changes in multiple myeloma cell lines to understand the molecular mechanisms underlying the downregulation of DAZAP2." (PMID 22792345, 2012). "DAZAP2 is also implicated in diseases, with its downregulation reported in multiple myeloma." (PMID 40833112, 2025). "To further understand the molecular mechanism underlying this deregulation, we analyzed epigenetic changes associated with DAZAP2 in multiple myeloma, given that aberrant methylation of promoter contributes to tumorigenesis by inducing transcriptional suppression and tumor suppressor inactivation." (PMID 22792345, 2012). "It is indicated that the promoter hypermethylation played a major role in downregulation of DAZAP2 gene expression in multiple myeloma." (PMID 22792345, 2012). "The present study was conducted to evaluate the mechanism of DAZAP2 downregulation and determine the methylation status of its promoter in multiple myeloma cells." (PMID 22792345, 2012). "We further correlated DAZAP2 expression with normal plasma cells and malignant myeloma cells, as well as the molecular subtypes which the dataset includes 8 genetic subtypes (MY, PR, LB, MS, HP, CD-1, CD-2, and MF) from 351 newly diagnosed myeloma cases." (PMID 22792345, 2012). "Our previous studies showed that DAZAP2 was the most profoundly downregulated gene in bone marrow mononuclear cells from multiple myeloma patients." (PMID 22792345, 2012). "The present work provided the direct evidence between methylation of DAZAP2 promoter and downregulation of DAZAP2 in multiple myeloma cell lines." (PMID 22792345, 2012). "Our previous studies had shown that DAZAP2 was profoundly downregulated in bone marrow mononuclear cells from multiple myeloma patients." (PMID 22792345, 2012). "Patients with multiple myeloma have DAZAP2 downregulation because of promoter methylation." (PMID 33175867, 2020). "This study warrants further investigation of DAZAP2 and its potential role in multiple myeloma." (PMID 22792345, 2012). "DAZAP2 promoter methylation might be involved in tumorigenesis of multiple myeloma and this would be helpful for the diagnosis and treatment of multiple myeloma patients." (PMID 22792345, 2012). "Interestingly, we extended and confirmed our previous discovery that DAZAP2 was significantly downregulated in multiple myeloma cells by using a large uniform dataset (P = 0.004)." (PMID 22792345, 2012). "We previously reported that DAZAP2 was downregulated in newly diagnosed multiple myeloma and this may influence the growth and survival of multiple myeloma cell." (PMID 22792345, 2012). "We also found that M. Sss I methylase could inhibit the luciferase activity, whereas demethylation using 5-aza-2′-deoxycytidine treatment rescued the expression of DAZAP2 for multiple myeloma cell lines." (PMID 22792345, 2012).
Azoospermia (4 papers, 2012 to 2026). Absence of any measurable level of sperm,whereby spermatozoa cannot be observed even after centrifugation of the semen pellet. "The DAZAP2 (Deleted in Azoospermia-associated Protein 2) gene encodes an azoospermia-related protein that plays key roles in spermatogenesis, cell cycle regulation, and transcriptional regulation." (PMID 42027905, 2026). "TRAF4 amplifies IL-25-mediated signaling by activating the E3 ligase smadubiquitin regulatory factor 2, leading to the ubiquitylation and subsequent degradation of the inhibitory protein, deleted in azoospermia DAZ-associated protein 2 (DAZAP2)." (PMID 35406669, 2022). "TRAF6 activates the NF-κB pathway while TRAF4 activates the MAPK pathway through degradation of the inhibitory protein DAZAP2 (deleted in azoospermia DAZ-associated protein 2) by Smad ubiquitin regulatory factor 2 (SMURF-2)." (PMID 36311787, 2022). "DAZAP2 (deleted in azoospermia associated protein 2) had originally been identified as an interacting protein of germ-cell-specific RNA-binding proteins DAZ (deleted in azoospermia).The evolutionary conserved DAZAP2 protein functions as a TCF-4 interacting partner." (PMID 22792345, 2012).
COVID-19 (2 papers, 2024 to 2025). A disease caused by infection with severe acute respiratory syndrome coronavirus 2. "Molecular characterization of DAZAP2/VTA1/KLF5-knockout cells highlights the involvement of genes related to the coagulation system in determining the severity of COVID-19." (PMID 38168026, 2024).
prostate carcinoma (2 papers, 2017 to 2023). A carcinoma that arises from epithelial cells of the prostate gland. "Fourteen DNA repair genes and 15 hormone-regulated genes contributed to the high trigger score for the 7p14.3 variant, of which DAZAP2, DDX18, SET, and XRCC5 were also significantly deregulated in SPOP mutant as compared to SPOP wild-type human prostate carcinoma cases." (PMID 28663546, 2017).
atherosclerosis (1 paper, 2022). A disease characterized by the build-up of fatty material and calcium deposition in the arterial wall resulting in partial or complete occlusion of the arterial lumen. "The biological function and their roles in atherosclerosis progression for the other genes, including DAZAP2, ARL6ip, CDK7, LIMS, HBP1, and DNAJB6, remain to be investigated." (PMID 35795669, 2022).
depression (1 paper, 2019). "In this study we performed an EWAS of depression symptomatology in a large cohort of monozygotic twins with two different statistical approaches and we identified DNA methylation levels in KLK8 and DAZAP2 genes to be most associated with the depression symptomatology score." (PMID 31477683, 2019). "Therefore, possible link between DAZAP2 and depression symptomatology requires further investigation." (PMID 31477683, 2019). "In conclusion, we have performed EWAS of depression symptomatology score in a unique cohort of elderly monozygotic twins and identified blood methylation levels at KLK8, DAZAP2, MAD1L1, SLC29A2, AKT1, and other genes, as well as several DMRs across the genome to be associated with this trait." (PMID 31477683, 2019).
osteoarthritis (1 paper, 2024). A noninflammatory degenerative joint disease occurring chiefly in older persons, characterized by degeneration of the articular cartilage, hypertrophy of bone at the margins and changes in the synovial membrane. "Furthermore, DEGs identified from DAZAP2-KO cells are enriched in the “Osteoarthritis pathway” and the pathway named as “Role of osteoblasts in rheumatoid arthritis signaling”." (PMID 38168026, 2024).
virus infection (1 paper, 2025). "Alternatively, DAZAP2 knockout may disrupt cellular homeostasis, rendering cells more susceptible to viral infection." (PMID 40833112, 2025). "In this study, we identify DAZAP2 as a potent pan-coronavirus restriction factor that inhibits viral infection through dual mechanisms: blocking virion fusion with both endolysosomal and plasma membranes, and suppressing genomic RNA replication." (PMID 40833112, 2025). "The stronger antiviral effect observed in bronchial epithelial cells may highlight the importance of DAZAP2 in protecting the lower respiratory tract from viral infection." (PMID 40833112, 2025). "Although DAZAP2 was shown to restrict SARS-CoV-2 infection, potentially through regulation of SERPINE1 expression, how it impacts the life cycle of virus infection and whether it functions in vivo remain to be elucidated." (PMID 40833112, 2025).
tumor (4 papers, 2014 to 2023). "Higher expression of the first exon of DAZAP2 was associated with higher meat quality index and this relationship could be due to cell proliferation given that this gene is a potential tumor suppressor." (PMID 33175867, 2020). "Further comprehensive analysis based on TCGA data indicated that the expression level of 3 genes (AVEN, DAZAP2, DNAJB1) were significantly higher in GC tumor tissues than in normal tissues." (PMID 36465351, 2022).
cancer (2 papers, 2012 to 2019). A tumor composed of atypical neoplastic, often pleomorphic cells that invade other tissues. "Of additional interest, for some of the genes confirmed here, such as DAZAP2 and KLF11, very little is known about their involvement in cancer and metastasis." (PMID 23113900, 2012). "However, DAZAP2 is essential for neural patterning in Xenopus laevis embryos, and KLF11 is an activator of embryonic and fetal beta-like globin genes, again pointing to a connection between regulation of embryonic development and cancer invasion." (PMID 23113900, 2012).
infection (2 papers, 2024 to 2025). The state of being infected such as from the introduction of a foreign agent such as serum, vaccine, antigenic substance or organism. "Upon viral challenge, viral loads in the lungs were significantly higher in knockout mice than the WT mice, confirming the protective role of DAZAP2 during infection." (PMID 40833112, 2025). "We first confirmed the antiviral activity of DAZAP2 in the context of infection with authentic SARS-CoV-2." (PMID 40833112, 2025). "To further investigate the restrictive function of DAZAP2, we cross-bred Dazap2−/− mice with human ACE2 knock-in mice (hACE2) to enable infection by the original SARS-CoV-2 strain." (PMID 40833112, 2025). "Despite these disruptions, infection efficiency was still significantly increased in DAZAP2-edited cells as compared to the controls." (PMID 40833112, 2025). "To determine the stage of infection at which DAZAP2 acts, we infected DAZAP2-edited cells with murine leukemia retrovirus (MLV)-based pseudoviruses bearing the spike protein of SARS-CoV-2 or, as a control, the glycoprotein of vesicular stomatitis virus (VSV-G)." (PMID 40833112, 2025). "DAZAP2 knockout significantly enhanced infection by all tested coronaviruses." (PMID 40833112, 2025). "Similarly, overexpression of human DAZAP2 inhibited infection by the betacoronavirus HCoV-OC43 and the alphacoronavirus porcine epidemic diarrhea virus (PEDV)." (PMID 40833112, 2025). "Infection of these gRNA-expressing A549-AC lines with SARS-CoV-2 at various MOI conditions produced consistent phenotypes: (i) knocking out pro-viral ATP6V0D1 or DPAGT1 increased cell viability and (ii) knocking out anti-viral DAZAP2, VTA1, or KLF5 decreased cell viability." (PMID 38168026, 2024).
DAZAP2 also shares sentences with these, for which no sentence is quoted: rheumatoid arthritis (1 paper).